LMNB2 (lamin B2)
Description:
Lamins are intermediate filament proteins that assemble into a filamentous meshwork, and which constitute the major components of the nuclear lamina, a fibrous layer on the nucleoplasmic side of the inner nuclear membrane. Lamins provide a framework for the nuclear envelope, bridging the nuclear envelope and chromatin, thereby playing an important role in nuclear assembly, chromatin organization, nuclear membrane and telomere dynamics. The structural integrity of the lamina is strictly controlled by the cell cycle, as seen by the disintegration and formation of the nuclear envelope in prophase and telophase, respectively.
Synonyms: LMN2; EPM9; LAMB2; MCPH27
Tractability: PROTAC: UniProt records ubiquitination sites on it; ubiquitination databases record sites on it; its protein half-life has been measured.
Target class: Structural protein
Gene: Protein-coding gene on chromosome 19 (2,427,638 to 2,456,992, reverse strand). Ensembl gene ENSG00000176619.
Subcellular location: Nucleus lamina
Subcellular location (Human Protein Atlas): Nuclear membrane
Gene Ontology:
Molecular function: identical protein binding; protein binding; structural constituent of cytoskeleton
Biological process: heterochromatin formation; nuclear envelope organization; nuclear migration; nuclear pore localization; protein localization to nuclear envelope; cytoskeleton organization
Cellular component: nuclear membrane; nuclear lamina
Genetic constraint (gnomAD): Loss-of-function variants: 16 observed, 60.93 expected, observed/expected ratio (o/e) 0.26, 90% interval 0.18 to 0.4. The upper end of that interval is the gene's LOEUF score, 0.4, which puts it in group 1 of 6, group 1 being the genes least tolerant of losing a copy. Missense variants: 770 observed, 820.26 expected, observed/expected ratio (o/e) 0.94, 90% interval 0.88 to 1. Synonymous variants: 388 observed, 355.19 expected, observed/expected ratio (o/e) 1.09, 90% interval 1 to 1.19.
Homologues: Orthologues: chimpanzee LMNB2 (99% identical), macaque LMNB2 (98% identical), dog LMNB2 (90% identical), pig LMNB2 (89% identical), mouse Lmnb2 (82% identical), tropical clawed frog lmnb2 (72% identical), rat Lmnb2 (69% identical), zebrafish lmnb2 (65% identical). Paralogues in human: LMNB1 (56% identical), LMNA (51% identical), PRPH (21% identical), KRT8 (21% identical), KRT75 (20% identical), VIM (20% identical), DES (20% identical), GFAP (20% identical), NEFM (20% identical), KRT18 (20% identical), KRT5 (20% identical), KRT6B (20% identical), and 56 more.
Diseases named in the same sentence as LMNB2 in open-access papers:
LMNB2 is named in the same sentence as 79 diseases in open-access papers, as found by Europe PMC text mining. Sharing a sentence is not in itself a finding about the gene and the disease. The quoted sentences say what the papers report.
colorectal cancer (12 papers, 2017 to 2025). A primary or metastatic malignant neoplasm that affects the colon or rectum. "Lamin B2 maintains chromosome integrity by ensuring proper spindle assembly and a decrease in Lamin B2 expression has been associated with chromosomal instability in colorectal cancer cell lines." (PMID 32402076, 2020). "Furthermore, Lamin B2 depletion shows chromosomal imbalances in colorectal cancer cells and associates with the spindle machinery, further suggesting the role of lamins in chromosome segregation in mitotic cells." (PMID 32337580, 2020). "Upregulation of LMNB2 expression promoted cancer cell proliferation and indicated worse disease-free survival in colorectal cancer and bladder cancer." (PMID 36405011, 2022). "The high expression of LMNB2 in colorectal cancer tissues is significantly related to the clinicopathological characteristics of the patients and the shorter overall and disease-free cumulative survival." (PMID 33782407, 2021). "This study explored the biological functions of LMNB2 in the progression of colorectal cancer and explored the possible molecular mechanisms." (PMID 33782407, 2021). "Here, we show using whole-genome expression profiling that Lamin A/C or Lamin B2 depletion in an otherwise diploid colorectal cancer cell line (DLD1) deregulates transcript levels from specific chromosomes." (PMID 26921073, 2017). "The increase in aneuploid cells upon Lamin B2 Kd is consistent with the known impact of Lamin B2 depletion in colorectal cancer cells." (PMID 26921073, 2017). "In summary, these findings not only indicate that LMNB2 promotes the proliferation of colorectal cancer by regulating p21-mediated cell cycle progression, but also suggest the potential value of LMNB2 as a clinical prognostic marker and molecular therapy target." (PMID 33782407, 2021). "Interestingly, Lamin B2 knockdown shows chromosomal gains in the otherwise diploid colorectal cancer cells (DLD1)." (PMID 32337580, 2020). "Lamin B2 maintains genomic stability and chromosome segregation in colorectal cancer cells." (PMID 26921073, 2017). "LMNB2 upregulation could promote colorectal cancer progression by regulating p21 expression." (PMID 36405011, 2022). "In addition, LMNB2 was significantly upregulated in colorectal cancer." (PMID 36405011, 2022). "However, the role of LMNB2 in colorectal cancer (CRC) is poorly understood." (PMID 33782407, 2021). "In colorectal cancer (CRC), NOP2 promotes m5C methylation of LMNB2 mRNA and enhances its stability, increasing LMNB2 protein levels." (PMID 41462962, 2025). "To achieve this in B-type lamins, we CRISPR-engineered HCT116 colorectal carcinoma epithelial cells and knocked in the mini auxin-inducible degron and mClover at the end of endogenous lamin B1 (LMNB1) and lamin B2 (LMNB2) gene loci." (PMID 38519987, 2024). "Lamin B2 localizes outside the spindle poles during mitosis and has a critical role in preventing CIN in colorectal cancers by maintaining spindle pole stability and spindle assembly." (PMID 32337580, 2020). "We found that LMNB2 was significantly upregulated in primary colorectal cancer tissues and cell lines, compared with paired non-cancerous tissues and normal colorectal epithelium." (PMID 33782407, 2021). "In contrast, Lamin B2 was shown to be a differentially expressed protein between colorectal cancers with and without CIN—with increase in Lamin B2 expression conferring protection against CIN." (PMID 26921073, 2017).
laminopathies (7 papers, 2016 to 2021). "In conclusion, our findings establish heterozygous variants in LMNB1 and LMNB2 as causes of primary microcephaly, implicating the nuclear lamina in its etiology and defining a novel form of laminopathy." (PMID 33033404, 2021). "We identify dominant pathogenic variants in LMNB1 and LMNB2 as a genetic cause of primary microcephaly, implicating a major structural component of the nuclear envelope in its etiology and defining a new form of laminopathy." (PMID 33033404, 2021). "Similar to lamin-A/C-related laminopathies, while LMNB1 and LMNB2 are also linked to disease, very few if any diseases have been linked to mutations in the LMNB1 and LMNB2 genes." (PMID 34455929, 2021). "Counterstaining with Lamin B1 in Lamin A/C-depleted cells and Lamin A/C upon Lamin B2 Kd revealed distorted nuclear shapes, nuclear invaginations, blebbing, and nuclear furrows as found in Lamin A/C- and B1-depleted HeLa cells and in cells derived from laminopathies." (PMID 26921073, 2017).
lung carcinoma (6 papers, 2017 to 2025). "LMNB2, a diagnostic and prognostic biomarker in lung cancer, correlates with genomic instability and proliferation potentially amplified by M2-derived cytokines." (PMID 40165975, 2025). "Based on all the pathways given, SOD, NFKB, TGF beta, C-Myc, STAT3, Lamin-B2, Macrophage mannose receptor 1, and Histone H1.0 proteins attracted attention, which was also observed in RNA-seq, and they have also been implicated in mediating lung cancer." (PMID 35745729, 2022). "In lung adenocarcinoma, KLF16 enhances the transcription activity of LMNB2 and promotes lung cancer cell growth and invasion." (PMID 40366008, 2025). "Subsequently, the role of LMNB2 in the development of lung cancer was investigated, and results showed that the depletion of LMNB2 inhibited the proliferation and invasion of H1299 and H1975 cells." (PMID 35387557, 2022). "In conclusion, KLF16 can be used as a potential therapeutic and preventive biomarker in lung cancer treatment and prognosis by actively regulating the expression of LMNB2." (PMID 35387557, 2022). "Among several targets, the human LMNB2 gene, which locates in chromosome 19p13.3 and encodes a 68-kDa protein, was a potential target for KLF16 in lung cancer development." (PMID 35387557, 2022). "To investigate the role of lamin B2 in NSCLC growth, we transiently knocked down LMNB2 with LMNB2-RNAi or overexpressed LMNB2 with GFP-LMNB2 vector in A549 and H1299 lung cancer cell lines with their corresponding controls." (PMID 29285216, 2017). "Lung cancer samples from the The Cancer Genome Atlas (TCGA) showed high lamin B2 mRNA expression in NSCLC than in normal tissues." (PMID 29285216, 2017). "Opposingly, lamin B2 overexpression unambiguously surfaced as an unfavorable event in lung cancer." (PMID 38067205, 2023). "In summary, KLF16 acts as an oncogene in lung cancer by regulating the expression of LMNB2." (PMID 35387557, 2022). "Here, a positive correlation was found between KLF16 and LMNB2 in lung cancer tissues." (PMID 35387557, 2022). "Lung cancer patients with high levels of LMNB2 expression had shorter lifespans." (PMID 35387557, 2022). "Furthermore, qRT-PCR, immunoblotting, luciferase reporter and rescue assays were carried out to investigate the relationship between KLF16 and LMNB2 in lung cancer cell growth, migration and tumorigenesis." (PMID 35387557, 2022). "A luciferase reporter assay was performed to verify the correlation between LMNB2 and KLF16, and the results showed that KLF16 might transcriptionally regulate LMNB2 expression in lung cancer." (PMID 35387557, 2022). "Our study illustrates the mechanism of KLF16 in lung cancer progression-positive regulation of LMNB2 expression and suggests that LMNB2 level may serve as an indicator of prognosis for patients with lung cancer." (PMID 35387557, 2022). "Although our study illustrated a story that KLF16 upregulated LMNB2 to promote the growth, proliferation, migration and tumorigenesis of lung cancer cells, whether other proteins participate in KLF16 driving lung cancer development should be determined in the future." (PMID 35387557, 2022). "Next, we investigated whether KLF16 promoted lung cancer progression through LMNB2." (PMID 35387557, 2022). "In addition, the overall survival of patients with high LMNB2 expression levels was relatively poor, indicating that LMNB2 may be a prognostic indicator for lung cancer." (PMID 35387557, 2022). "Further, our in vivo studies with H1975 lung cancer cells demonstrated that this combination is effective through multiple pathways, including AMPK, NF-κB, Lamin B2, and JAK-STAT, which regulates mitochondrial homeostasis, inflammation, oxidative stress, and apoptosis." (PMID 35745729, 2022). "However, the relationship between lamin B2 and lung cancer has never been reported." (PMID 29285216, 2017).
acquired partial lipodystrophy (5 papers, 2017 to 2022). A lipodystrophy characterized by the association of lipoatrophy of the upper part of the body and lipohypertrophy of the thighs. "Only 4 mutations were identified in LMNB2, and these were associated with acquired partial lipodystrophy." (PMID 36552829, 2022). "The first reported heterozygous mutation of LMNB2 gene is a case of acquired partial lipodystrophy, also called Barraquer-Simons syndrome." (PMID 28854936, 2017). "Indeed, enrichment of heterozygous LMNB2 variants in acquired partial lipodystrophy patients has been described." (PMID 35132494, 2022). "Mutations in LMNB2 may cause susceptibility to acquired partial lipodystrophy." (PMID 35132494, 2022).
lung adenocarcinoma (5 papers, 2021 to 2025). A carcinoma that arises from the lung and is characterized by the presence of malignant glandular epithelial cells. "FANCE is reported to be a vital factor influencing the poor survival of FANCE-deficient cells among breast cancer cell lines, and upregulation of LMNB2 is associated with significantly poorer prognosis in lung adenocarcinoma patients." (PMID 33499863, 2021). "The expression level of LMNB2 in lung adenocarcinoma (LUAD) was measured, and results showed that LMNB2 was highly expressed in LUAD tissues compared with that in normal tissues." (PMID 35387557, 2022). "The upregulation of KLF16 and LMNB2 was observed in lung adenocarcinoma samples, which accelerated the proliferation and invasion of H1299 and H1975 cells." (PMID 35387557, 2022).
non-small cell lung carcinoma (5 papers, 2017 to 2025). A group of at least three distinct histological types of lung cancer, including non-small cell squamous cell carcinoma, adenocarcinoma, and large cell carcinoma. "This aligns with another study showing consistent expression trends of LMNB2 and PD-L1 in non-small cell lung cancers under various drug treatments." (PMID 40483310, 2025). "Lamin B2 promotes the malignant phenotype of non-small cell lung cancer cells by interacting with micro chromosome maintenance protein 7 and Cyclin D1, both of which increase tumor motility and tumor cell epithelial-mesenchymal transition." (PMID 35745729, 2022). "We investigated the role of lamin B2 in non-small cell lung cancer (NSCLC)." (PMID 29285216, 2017). "LMNB2, a B type nuclear lamin, binds to the C-terminus of MCM7 and competes with the binding of the tumor suppressor RB protein, thus regulates human non-small-cell lung cancer progression." (PMID 33102573, 2020).
ovarian carcinoma (4 papers, 2016 to 2019). A malignant neoplasm originating from the surface ovarian epithelium. "In ovarian cancer, lamin B2 is overexpressed, whereas its low expression in prostate cancer correlates with lymph node metastasis." (PMID 29285216, 2017). "Recently a number of proteins overexpressed in both PCOS and ovarian cancer, such as superoxide dismutase, fibrinogen γ, vimentin, calreticulin, malate dehydrogenase, and lamin B2, have been identified, revealing subgroups of women with PCOS and with an increased risk of developing this malignancy." (PMID 27725832, 2016). "Identification of a number of proteins overexpressed in both PCOS and ovarian cancer, such as superoxide dismutase, calreticulin, vimentin, fibrinogen γ, lamin B2, and malate dehydrogenase, assured the identification of women with PCOS with an increased risk of developing this malignancy." (PMID 27725832, 2016).
Progressive myoclonic epilepsy (4 papers, 2021). "The report of LMNB2-related progressive myoclonus epilepsy and ataxia due to missense homozygous c.473G>T variant." (PMID 34466237, 2021). "In addition to genetic lipodystrophy, lamin B2 has been recently involved in progressive myoclonic epilepsy and in severe intellectual deficiency syndromes with severe microcephaly, widening the spectrum of genetic conditions associated with this lamin alteration." (PMID 35011612, 2021). "It has been reported that a mutation in LMNB2 could lead to progressive myoclonus epilepsy." (PMID 34404356, 2021).
breast carcinoma (3 papers, 2020 to 2023). "Prognostic analyses further revealed that LMNA, LMNB1, and LMNB2 expression all had prognostic value in the distant metastasis‐free survival (DMFS) of breast cancer patients." (PMID 37218524, 2023). "Importantly, either STING or cGAS KO or LMNB2 overexpression in donor breast cancer cells strongly decreased induction of paracrine propapoptotic effect by paclitaxel." (PMID 31937780, 2020).
glioma (3 papers, 2022 to 2025). A benign or malignant brain and spinal cord tumor that arises from glial cells (astrocytes, oligodendrocytes, ependymal cells). "In the central nervous system, elevated expression of LMNB2 is associated with the rapid progression of glioma." (PMID 40366008, 2025). "Among these, LMNB2, encoding nuclear type B2 Lamin, is significantly upregulated in glioma, and it has been observed that the high expression of the laminin family members in glioma cells is associated with rapid progression of the disease, suggesting a direct role in gliomagenesis." (PMID 40507925, 2025). "They asserted that all three of the human genes encoding for lamin isoforms (LMNA, LMNB1, and LMNB2) are significantly upregulated in glioma tissues compared with normal brain tissues and their silencing dramatically suppresses glioma progression in both in vitro and in vivo mouse models." (PMID 35883635, 2022).
bladder cancer (2 papers, 2022 to 2025). "Besides, it was also revealed that LMNB2 expression was upregulated in human bladder cancer tissues, and it promoted the proliferation of bladder cancer cells via transcriptional activation of CDCA3 expression." (PMID 40366008, 2025).
bladder urothelial carcinoma (2 papers, 2024 to 2025). "In addition, we revealed that up-regulated expression levels of LMNB2 were associated with shorter PFS in ACC, bladder urothelial carcinoma (BLCA), breast invasive carcinoma (BRCA), LGG, MESO, pancreatic adenocarcinoma (PAAD), PRAD and SARC." (PMID 39774004, 2024).
esophageal carcinoma (2 papers, 2022 to 2024). A primary or metastatic malignant neoplasm involving the esophagus. "LMNB2 is a lamin protein known to regulate nuclear stability and gene expression, with noted upregulation in breast, colorectal and oesophageal cancers." (PMID 35682908, 2022).
glioblastoma (2 papers, 2020 to 2024). The most malignant astrocytic tumor (WHO grade IV). "Western blotting of the levels of nuclear lamins showed a decrease in lamin B1 in both glioblastoma cell lines and lamin B2 in U251MG cells under arginine deprivation in combination with canavanine treatment." (PMID 33008000, 2020).
hepatocellular carcinoma (2 papers, 2021 to 2025). A malignant tumor that arises from hepatocytes. "To explore the impact of LMNB2 on immune infiltration, we manipulated LMNB2 expression in mouse hepatoma Hepa1-6 cells, creating overexpression and knockdown groups." (PMID 40483310, 2025).
lipodystrophies (2 papers, 2019 to 2021). "Up to now, five patients with lipodystrophy and metabolic disorders have been reported carrying a mutation in the coding region of LMNB2." (PMID 35011612, 2021). "In pathology, dysfunctions of lamin B2 have been linked to lipodystrophy as early as 2006, but since then, only a very few cases of such a disorder have been reported." (PMID 35011612, 2021). "Altogether, these results suggest that mutations in lamin B2 could produce premature senescence and partial lipodystrophy features as observed with certain mutants of lamin A/C." (PMID 35011612, 2021). "Indeed, up to now, only five patients with lipodystrophies due to variants in lamin B2 have been reported in the literature and have been described as acquired partial lipodystrophy, mainly because of a sporadic presentation." (PMID 35011612, 2021). "By performing high throughput sequencing on a panel of genes involved in lipodystrophies, we identified a heterozygous mutation in LMNB2 gene (c.700C > T p.(Arg234Trp)) in a female patient presenting early onset type II diabetes, hypertriglyceridemia, and android fat distribution." (PMID 35011612, 2021). "As said above, mutations in lamin A/C, lamin B2, or ZMPSTE24 gene or alterations of prelamin A maturation are the cause of laminopathies featuring lipodystrophy." (PMID 30781376, 2019). "Up to now, the causative role of lamin B2 in lipodystrophy has not been clearly established, especially because it is likely associated with attenuated partial forms of the disease that are not always investigated and/or correlated with molecular analysis." (PMID 35011612, 2021).